VDR (vitamin D receptor)
Diseases named in the same sentence as VDR in open-access papers (continued):
Sharing a sentence is not in itself a finding about the gene and the disease.
vitamin D deficiency (continued). "The vitamin D receptor (VDR) and the 1-alpha-hydroxylase-converting enzyme expressed in pancreatic beta cells suggests a direct impact on insulin secretion, where vitamin D insufficiency could interfere with normal insulin release by altering calcium flux." (PMID 40869611, 2025). "Recent studies have explored various aspects of the relationship between vitamin D deficiency and GDM, including the mechanisms by which vitamin D affects glucose metabolism, the role of the vitamin D receptor gene, and the impact of routine vitamin D supplementation before and during pregnancy." (PMID 39749014, 2024). "Nevertheless, this is the first study in Saudi Arabia to evaluate the correlation between GDM and the FokI VDR polymorphism, considering factors such as the family history of diabetes, previous history of GDM, obesity, parity, vitamin D deficiency, BMI, and age." (PMID 38882352, 2024). "In patients with CKD, the frequency of vitamin D deficiency would increase with CKD progression, which could be caused by various factors, such as increased fibroblast growth factor 23 level, reduced vitamin D receptor, or the accumulation of uremic toxin." (PMID 38633934, 2024). "In association with vitamin D deficiency, VDR gene FokI polymorphism, not TaqI, is a genetic risk factor for complicated pneumonia in Egyptian children." (PMID 37559014, 2023). "This difference may therefore have influenced our results, as latitude has been suggested to influence vitamin D insufficiency and may therefore also impact on VDR signaling." (PMID 36983024, 2023). "Notably, the VDR mRNA expression was higher in SLE patients vs. CS, in active vs. inactive SLE patients, and in participants of both study groups with vitamin D deficiency, higher calcitriol levels, and TT FokI VDR genotype carriers." (PMID 36360253, 2022). "Vitamin D deficiency is recognized as a general risk factor for CRC; when vitamin D binds to VDR it behaves as a transcription factor for many genes, exerting profound antimitogenic and differentiating effects on many normal and malignant cells, including colon cancer cells." (PMID 35889921, 2022). "A single study identified that VDR genotype variants (rs2228570), the same as in our research, are not risk factors for serum 25-OH/D depletion or vitamin D deficiency." (PMID 36233147, 2022). "In both the current report in VDR null animals, as well as our previous report with vitamin D deficiency, we do not find evidence for a direct correlation between circulating serum calcium and colonic tumor number." (PMID 35662320, 2022). "Notably, the mRNA VDR expression was higher in SLE patients vs. CS, in active vs. inactive SLE patients, and in participants of both study groups with vitamin D deficiency, higher calcitriol levels, and TT FokI genotype carriers." (PMID 36360253, 2022). "It has been suggested that vitamin D deficiency and lack of vitamin D receptor (VDR) activation can aggravate this respiratory syndrome associated with SARS-CoV-2, as it triggers a wounding response in lung stellate cells." (PMID 35458189, 2022). "Results of our study show that the rs2228570 VDR polymorphism is not a risk factor for reduced serum 25-OH vitamin D, either vitamin D deficiency or its suboptimal provision." (PMID 34621381, 2021). "The vitamin D receptor (VDR) exists in bronchial epithelial cells and is an important cause of pulmonary fibrosis partly because vitamin D deficiency can regulate TGF-β signalling by suppressing phosphorylated Smad-2/3 and activating the renin-angiotensin system (RAS) activity." (PMID 35115954, 2021). "Genotype variants of VDR rs2228570 are not risk factors for reduced serum 25-OH Vitamin D, either vitamin D deficiency or suboptimal provision." (PMID 34621381, 2021). "On the other hand, some studies have represented that vitamin D deficiency and also single nucleotide polymorphism (SNP) of VDR did not affect dysmenorrhea, pelvic pain, or infertility." (PMID 34362981, 2021).
vitamin D deficiency (continued). "Our research identified that that genotype variants of VDR rs2228570 are not risk factors for reduced serum 25-OH vitamin D or vitamin D deficiency in patients with various forms of thyroid pathology patients in the West-Ukrainian population." (PMID 34621381, 2021). "Furthermore, vitamin D supplementation for four months increased the expression level of intramyonuclear VDR and the size of muscle fibers in older women with vitamin D insufficiency." (PMID 33322706, 2020). "VDR knockout and vitamin D deficiency conditions seem to clearly indicate negative consequences for skeletal muscle homeostasis." (PMID 30830277, 2019). "Although, VDR polymorphisms are unlikely to play a major role in obesity-related phenotypes, as reported in a population of Caucasian adults, vitamin D deficiency has been associated with obesity in both pediatric and adult populations." (PMID 31252594, 2019). "We cannot exclude the possibility of vitamin D deficiency being a consequence rather than the cause of inflammatory response, as excess of 1,25(OH)2D is produced in an effort to up-regulate the VDR and 25(OH) is rapidly metabolized in this process." (PMID 31179282, 2019). "This may explain the inadequacy of cellular nutrition for vitamin D, as systematically reflected by the vitamin D receptor (VDR) and thus the low cellular survival in the pathological cases with vitamin D deficiency." (PMID 30408071, 2018). "Vitamin D deficiency was accompanied by elevated synthesis of renal CYP27B1 and VDR." (PMID 29552033, 2018). "1,25(OH)2D mediates its immune activity through binding to the vitamin D receptor (VDR) on target cells; thus receptor abnormalities as well as vitamin D deficiencies may impair host immunity toM.tb108." (PMID 30210785, 2018). "In conclusion, the VDR BsmI polymorphism was significantly associated with vitamin D deficiency and insulin resistance, but not with obesity." (PMID 28617856, 2017). "Further studies are required to elucidate whether treatment of vitamin D deficiency in SLE suppresses the IFN signature gene expression, possibly by the role of the vitamin D receptor present in plasmacytoid dendritic cells." (PMID 32185270, 2017). "At baseline, there was no significant trend in distribution of vitamin D deficiency status among VDR Fok-I variants (P-trend = 0.626)." (PMID 28811597, 2017). "VDR BsmI polymorphism was significantly associated with vitamin D deficiency and insulin resistance, but not with obesity in this population." (PMID 28617856, 2017). "Few studies have shown an association between vitamin D deficiency and glaucoma, and there are no previous studies relating VDR gene polymorphisms to the development of glaucoma." (PMID 27435453, 2016). "Vitamin D deficiency did not alter muscle mass but reduced muscle force over time, downregulated vitamin D receptor expression, and increased muscle lipid peroxidation but did not alter actin and myosin expression, fiber dimensions or twitch relaxation time." (PMID 26906744, 2016). "Vitamin D deficiency per se, as well as VDR mutations and VDR knock-out, has shown not to affect serum mineral concentrations, bone mineralization and fetal longitudinal bone growth." (PMID 27571350, 2016). "To assess the possible link between vitamin D deficiency and fibrosis formation, we decided to study the role TGF-β expression, the most important pro-fibrotic cytokine, and its relationship with the vitamin D receptor (VDR)." (PMID 25222475, 2014). "Severe vitamin D deficiency was not independently associated with collateralization, but it was significantly associated with the VDR genotypes." (PMID 24729966, 2014). "Alternatively, increased expression of the VDR and CYP2R1 may result from a homeostatic response of BALF cells to counter the effects of vitamin D deficiency." (PMID 23826346, 2013).
vitamin D deficiency (continued). "Currently, there is no information about the effects that long-term vitamin D deficiency can have on the brain later in life due to the short life span of VDR knockout mice." (PMID 21408608, 2011). "It is possible that individuals with certain VDR genotypes may be more sensitive to vitamin D insufficiency or may respond differently to supplementation as is the case in bone and prostate." (PMID 21209718, 2010). "The number of VDRs present in skeletal muscle declines with age; thus, strength in young adults, such as the participants in this study, may be less sensitive to vitamin D insufficiency because of the abundance of VDR in their myofibers." (PMID 21209718, 2010). "Importantly, IMAT formation may be prevented in ‘healthy’ skeletal muscle even under vitamin D deficiency or impaired VDR signalling, indicating the existence of an additional factor(s) contributing to IMAT formation in addition to vitamin D deficiency." (PMID 38533539, 2024). "The protection given by VDR activation may become compromised when the detoxification pathway is overwhelmed (e.g., by increased levels of LCA due to sustained high-fat diets) or under pathologies of vitamin D deficiency (e.g., rickets/osteomalacia)." (PMID 35889921, 2022). "A limitation of our study is that we could not assess 25(OH)D levels and genetic status of the analyzed patients, and thus, we cannot exclude the potential contribution neither of concomitant vitamin D deficiency nor of polymorphisms in VDR." (PMID 35166042, 2022). "In particular, LF has been shown to increase the expression of vitamin D receptor (VDR) in the colon of vitamin D deficient mice and a growing body of evidence suggests that vitamin D deficiency may play a central role in COVID-19 pathophysiology and mortality." (PMID 33498631, 2021). "Vitamin D deficiency and progressive reductions in serum calcitriol in the course of CKD also impair the response of the parathyroid gland to calcium due to reductions in parathyroid content of the calcium sensing receptor (CaSR), a gene directly stimulated by the calcitriol/VDR complex." (PMID 34950686, 2021). "Also, a study of both VDBP and VDR polymorphisms in CAD patients showed a strong association between the VDR (rs1544410, G > A) and VDBP (rs7041 T > G) genes polymorphisms and vitamin D deficiency, and the latter was also evaluated as a possible risk factor in CAD pathogenesis." (PMID 33863283, 2021). "While positive associations were found for 3 SNVs in VDR (rs59128934, rs7965274 and rs2853564), 2 SNVs in CYP24A1 (rs56229249 and rs34043203) and 2 in CYP2R1 (rs12794714 and rs10500804), indicating that the presence of such variations increase risk to vitamin D insufficiency." (PMID 32834827, 2020). "One explanation was that lack of VDR and vitamin D deficiency may not have the same influence on a disease." (PMID 32541827, 2020). "The high incidence of vitamin D deficiency in allogeneic HSCT patients, alongside the current controversy, emphasizes the need for further studies on the impact of vitamin D deficiency and VDR gene polymorphisms on clinical outcomes to define its role as a biomarker in this setting." (PMID 32582151, 2020). "However, the correction of vitamin D deficiency should be done wisely in order to avoid negative consequences of VDR overexpression and vitamin D toxicity." (PMID 30830277, 2019). "In our study, we found a reduced expression of VDR and increased expression of TGF-β and α-SMA in VDD+Nx rats, supporting the hypothesis that vitamin D deficiency is not only associated with renal tubulointerstitial damage and fibrosis but also with cellular phenotypic alteration." (PMID 30370270, 2018). "Although the effects of vitamin D on iNKT cells development have been elucidated, it is not clear as to whether vitamin D deficiency (or VDR knockout) results in a proinflammatory or anti-inflammatory state." (PMID 30046564, 2018).
vitamin D deficiency (continued). "We hypothesize that the increasing rates of vitamin D deficiency coupled with VDR dysfunction and a lack of gut microbiota diversity are the key drivers of the rise in autoimmune diseases in Western countries." (PMID 28066436, 2016). "Vitamin D receptor polymorphism is also important in evaluating the effect of vitamin D deficiency on thyroid autoimmunity, despite the existence of controversial reports of the absence of a role for functional vitamin D receptor polymorphism in the frequency of autoimmune thyroiditis." (PMID 25654127, 2015). "Thus, the effects of maternal vitamin D deficiency on placental structure are likely mediated through the decidua rather than directly via VDR signaling in the placenta." (PMID 26121239, 2015). "Parathyroid cells that have VDR and vitamin D deficiency, with or without low expression of VDR in these cells, causes an increase in circulating levels of the parathyroid hormone (PTH), which is responsible for a number of metabolic alterations in skeletal and non-skeletal tissues." (PMID 24747593, 2014). "Vitamin D deficiency and VDR gene polymorphism (FokI) act non-synergistically (p value < 0.4)." (PMID 23705897, 2013). "In this scenario, the decrease in VDR due to predisposing genetic or environmental factors, as well as vitamin D deficiency, could have a negative effect on the transcription of SIRT1 and could influence all the pathways underlying DN regulated by this protein." (PMID 39976627, 2025). "Unlike the potential fall risk posed by inadequate VDR stimulation of anti-inflammatory immunomodulatory cells, which can occur in the state of vitamin D deficiency, the presence of inflammation in conjunction with higher vitamin D levels may shift the balance of steroid hormone competition." (PMID 39796472, 2024). "Given the relatively higher incidence of vitamin D deficiency among Malaysian pregnant women and the high incidence of HDP in this population, we hypothesize that there may be associations between the risk of vitamin D deficiency and HDP with VDR genetic variants." (PMID 38530345, 2024). "Vitamin D deficiency is quite common in this patient group (67–85%) and may appear in a more severe form although the single-nucleotide polymorphism (Apa I, VDR Fok I, Taq I) of the vitamin D receptor (VDR) does not correlate with the risk of developing PCOS or with the severity of the disease." (PMID 35458211, 2022). "Additionally, we did not test how global vitamin D deficiency may impact neuronal function of VDR+ neurons or the effects of 1,25D3 on neuronal activity." (PMID 35620386, 2022). "In addition, Vitamin D receptor deletion results in longer mammary ducts (whereas the EDARV370A in mice increased branch density of the mammary glands), so the EDAR variant could counter the effects of vitamin D deficiency in mothers as well." (PMID 34618839, 2021). "However, the observation that neither Rnf20/40-deficient mice, nor patients with low expression of RNF20/40-dependent genes displayed vitamin D deficiency suggests that vitamin D supplementation alone would likely not be sufficient to compensate for decreased vitamin D receptor levels." (PMID 34088983, 2021). "This may be explained in part by a study showing that VDR-knockdown in C2C12 myotubes results in an increase in optic atrophy 1 (OPA1) abundance, which was proposed to be a compensatory mechanism to rescue deficits in mitochondrial function resulting from vitamin D deficiency." (PMID 33935807, 2021). "In the present study, mice carrying a functionally inactive VDR were exposed to the absence of vitamin D signaling already in the prenatal period, which appears to lead to more severe vulnerability to cardiovascular diseases than vitamin D deficiency developing in adult life." (PMID 32545499, 2020).
vitamin D deficiency (continued). "In the absence of association of the VDR polymorphisms observed in our study, the increased incidence of CRCs may be attributed to the high prevalence of vitamin D deficiency among Saudis, since substantial evidence suggests that vitamin D may play significant role in CRC risk." (PMID 27309378, 2016). "The FokI VDR polymorphism may have an independent association with collateralization, suggesting that genetic predisposition may contribute to different degrees of collateralization, independent of vitamin D deficiency." (PMID 24729966, 2014). "VDR expression is the main determinant of cell responsiveness to 1,25(OH)2D3 and is often downregulated in advanced CRC, which together with frequent vitamin D deficiency, implies that these patients would probably not benefit from the anticancer effects of 1,25(OH)2D318-20." (PMID 39494323, 2024). "Despite VDR polymorphisms have not been mentioned among the possible susceptibility genes for RLS in GWAS, it seems to be reasonable, due the possible role of vitamin D deficiency in the pathogenesis of RLS, to study the association between SNPs related with vitamin D and the risk for RLS." (PMID 26632733, 2015).